PPP1R9A (protein phosphatase 1 regulatory subunit 9A)
Description:
Binds to actin filaments (F-actin) and shows cross-linking activity. Binds along the sides of the F-actin. May be involved in neurite formation. Inhibits protein phosphatase 1-alpha activity (By similarity).
Synonyms: KIAA1222; Neurabin-I; FLJ20068; NRB1; NRBI
Tractability: Antibody: the Human Protein Atlas places it where antibodies can reach. PROTAC: ubiquitination databases record sites on it; its protein half-life has been measured.
Gene: Protein-coding gene on chromosome 7 (94,907,202 to 95,296,415, forward strand). Ensembl gene ENSG00000158528.
Subcellular location: Cytoplasm, cytoskeleton; Synapse, synaptosome
Subcellular location (Human Protein Atlas): Plasma membrane
Gene Ontology:
Molecular function: protein binding; actin filament binding
Biological process: actin filament organization; calcium-mediated signaling; neuron projection development
Cellular component: actin cytoskeleton; cytoplasm; dendrite; postsynaptic density; cytoskeleton; plasma membrane bounded cell projection; synapse
Genetic constraint (gnomAD): Loss-of-function variants: 56 observed, 138.63 expected, observed/expected ratio (o/e) 0.4, 90% interval 0.32 to 0.5. The upper end of that interval is the gene's LOEUF score, 0.5, which puts it in group 2 of 6, group 1 being the genes least tolerant of losing a copy. Missense variants: 1,385 observed, 1,609.8 expected, observed/expected ratio (o/e) 0.86, 90% interval 0.82 to 0.9. Synonymous variants: 486 observed, 574.54 expected, observed/expected ratio (o/e) 0.85, 90% interval 0.78 to 0.91.
Homologues: Orthologues: chimpanzee PPP1R9A (99% identical), macaque PPP1R9A (98% identical), dog PPP1R9A (89% identical), pig PPP1R9A (87% identical), rabbit PPP1R9A (85% identical), guinea pig PPP1R9A (84% identical), rat Ppp1r9a (83% identical), mouse Ppp1r9a (82% identical), tropical clawed frog ppp1r9a (54% identical), zebrafish ppp1r9a (42% identical), Drosophila melanogaster Spn (27% identical), Caenorhabditis elegans nab-1 (18% identical). Paralogues in human: PPP1R9B (28% identical), SAMD14 (9% identical).
Diseases named in the same sentence as PPP1R9A in open-access papers:
PPP1R9A is named in the same sentence as 26 diseases in open-access papers, as found by Europe PMC text mining. Sharing a sentence is not in itself a finding about the gene and the disease. The quoted sentences say what the papers report.
lymphoma (3 papers, 2020 to 2024). A malignant (clonal) proliferation of B- lymphocytes or T- lymphocytes which involves the lymph nodes, bone marrow and/or extranodal sites. "In addition, we found recurrent somatic mutations in the protein phosphatase 1 regulatory subunit 9 A (PPP1R9A), in FAT cadherins, and in the RUNX1T1 transcriptional repressor, suggesting their possible involvement in shaping the phenotype of lymphoma cells." (PMID 39478125, 2024).
Anxiety (2 papers, 2016 to 2023). Intense feelings of nervousness, tension, or panic often arise in response to interpersonal stresses. "In schizophrenia and bipolar disorder, the prefrontal cortical expression of PPP1R9A was altered and its gene product Neurabin regulates anxiety-like behavior in adult mice." (PMID 36449109, 2023). "A 2 Mb deletion impacting 15 genes–including PPP1R9A and the sarcoglycan epsilon (SGCE) gene - was found in a 12 year old girl (case 7D) referred for myoclonus dystonia, short stature, failure to thrive, severe anxiety and obsessive-compulsive behavior." (PMID 27363808, 2016).
Obesity (2 papers, 2015 to 2025). Accumulation of substantial excess body fat. "The orthologs of Spn, protein phosphatase 1, regulatory subunit 9A (PPP1R9A) and protein phosphatase 1, regulatory subunit 9B (PPP1R9B), are associated with piglet birth weight and pig food intake and human obesity." (PMID 26375667, 2015). "SNAP47 and PPP1R9A are associated with neuronal pathways and have to our knowledge not yet been studied in the context of obesity." (PMID 41225618, 2025).
schizophrenia (2 papers, 2022 to 2023). A major psychotic disorder characterized by abnormalities in the perception or expression of reality. "The results of the AWM extend this list with PPP1R9A, which encodes the protein Neurabin-1 and has been linked to dendritic spine loss in schizophrenia." (PMID 36061196, 2022).
coronary artery disease (1 paper, 2023). "PPP1R9A gene is involved in neurite formation, is associated to coronary artery disease, and is a prognostic marker in renal cancer." (PMID 36949158, 2023).
endometriosis (1 paper, 2025). The growth of functional endometrial tissue in anatomic sites outside the uterine body. "Through this analysis, we identified 42 genome-wide significant (5 × 10−8) genetic variants significantly associated with endometriosis, 6 of which were not reported previously: ABHD1/2p23.3, TMEM131/2q11.2, XRCC4/5q14.2, PPP1R9A/7q21.3, XKR6/8p23.1, and TRPS1/8p23.3." (PMID 40262193, 2025).
HCMV infection (1 paper, 2024). "Our findings indicate that HCMV infection disrupts PP1 function through the temporal dysregulation of at least nine recognized regulatory subunits, PPP1R10, PPP1R7, YLPM1, PPP1R11, PPP1R9A, PPP1R8 (NIPP1), PPP1R9B, PPP1R12C, and URI1." (PMID 39772267, 2024).
lung adenocarcinoma (1 paper, 2016). A carcinoma that arises from the lung and is characterized by the presence of malignant glandular epithelial cells. "Thus, we investigated the expression levels (in RPKM) of the three genes (NUP210, PKN1, and PPP1R9A) in each of the lung adenocarcinoma cell lines and compared it with that in SAEC." (PMID 27042856, 2016). "The number of lung adenocarcinoma cell lines aberrantly expressing NUP210, PKN1, and PPP1R9A was 26, 26, and 8, respectively." (PMID 27042856, 2016). "Regarding the other two genes (PKN1 and PPP1R9A), although the frequency of aberrant gene expression in the other 10 types of carcinoma was 0–12.0% (PKN1) and 0–12.0% (PPP1R9A), no lung adenocarcinoma tissue sample showed aberrant gene expression." (PMID 27042856, 2016).
cancer (3 papers, 2014 to 2016). A tumor composed of atypical neoplastic, often pleomorphic cells that invade other tissues. "By focusing on the three genes above (NUP210, PKN1, and PPP1R9A), we examined their functions and known relationships with cancer." (PMID 27042856, 2016). "Gain and amplification of 7q22.11q31.1 are associated with an increased expression of several genes postulated to be implicated in cancer, including RUNDC3B, PPP1R9A and ABCB1, a known multidrug resistance gene." (PMID 25057852, 2014). "PPP1R9A is upregulated both in benign and cancer prostatic tissues." (PMID 27042856, 2016).
tumor (2 papers, 2023 to 2025). "We found that gap junction signaling pathways (ADCY8 and PPP1R9A) were upregulated and cell adhesion signaling pathways (VSIR and HLA-C) were downregulated, which is associated with tumor growth metastasis." (PMID 37511481, 2023).
neurodevelopmental disorder (1 paper, 2016). A behavioral and cognitive disorder with onset during the developmental period that involves impaired or aberrant development of intellectual, motor, or social functions. "We identified genes containing CNVs previously considered to be VOUS to be new candidate genes for neurodevelopmental disorders (GIT1, MVB12B and PPP1R9A) demonstrating the utility of this strategy to index the clinical effects of CNVs." (PMID 27363808, 2016).
PPP1R9A also shares sentences with these, for which no sentence is quoted: primary central nervous system lymphoma (3 papers); bipolar disorder (1); breast carcinoma (1); B‐cell lymphoma (1); chronic lymphocytic leukemia (1); colon cancer (1); diffuse large B-cell lymphoma (1); Failure to thrive (1); heart disease (1); lung fibrosis (1); mantle cell lymphoma (1); myoclonus dystonia (1); neuroblastoma (1); plasma cell dyscrasia (1); prostate carcinoma (1).